CDK1 (cyclin dependent kinase 1)
Diseases named in the same sentence as CDK1 in open-access papers (continued):
Sharing a sentence is not in itself a finding about the gene and the disease.
liver cancer (continued). "Studies have shown that high expression of CDK1, CCNB1, and CCNA2 is associated with reduced overall survival in patients with liver cancer." (PMID 35463358, 2022). "Taken together, our results strongly indicated that liver cancer patients with an upregulated level of TOP2A, RRM2, NEK2, CDK1, and CCNB1 were associated with poor prognosis." (PMID 34681056, 2021). "The correlation between CDK1 expression and immune cell gene markers revealed that CDK1 regulates liver cancer tumor immunity through multiple immune cell populations." (PMID 34187556, 2021). "Taken together, our results suggest TOP2A, RRM2, NEK2, CDK1, and CCNB1 as HCC-associated hub genes that can serve as potential prognostic biomarkers in liver cancer." (PMID 34681056, 2021). "Among them, MCODE 1 mainly comprised the mutations of CDK1, KIF2C, KIF18A, CENPA, and PLK1, which take part in the tumorigenesis and progression of liver cancer." (PMID 34414037, 2021). "Ccne1 overexpression cause liver tumor development in mice, Cdk2 plays a key role in cell cycle progression in hepatocyte, and cyclin-dependent kinase 1 (Cdk1) is essential for cell division of liver cancer." (PMID 32570707, 2020). "CCAT1 upregulates CDK1 in liver cancer cells by binding to and sponging miR-490-3p, a micro RNA known to downregulate CDK1 expression." (PMID 31080551, 2019). "Therefore, designing anti-liver fibrosis and liver cancer drugs targeting CDK1 has broad application prospects." (PMID 40332418, 2025). "Although our in silico findings suggest that Digoxin may inhibit liver cancer growth via CDK1 regulation, its therapeutic use remains limited due to several factors." (PMID 41048345, 2025). "Similarly, studies showed that quercetin reduced the expressions of CDK1, and inhibited the proliferation of liver cancer." (PMID 37393234, 2023). "Therefore, the expression levels of AURKA, BIRC5, CCNB1, CDK1, CDKN3 and TYMS served as diagnostic markers for liver cancer patients." (PMID 37393234, 2023). "Our results suggested that high expression levels of CDK1 could increase immune activation and cytotoxicity of the immune system in liver cancer by increasing the infiltration of immune cells." (PMID 34187556, 2021). "Notably, it was previously foundthat inhibition of the MAPK signaling pathway in liver cancer cellstriggered a decrease in CDK1 expression." (PMID 25652240, 2015). "Second, lack of other factors may be involved in the progress of HCC, including smoking status, eating habits, region, drinking status and family history of liver cancer which could be used to further evaluate the relationship between CDK1-4,6 expression and HCC." (PMID 35193513, 2022). "Therefore, miR-125b-2-3p and lncRNAP26302 may have a coordinative effect on this pathway, together promoting the expression of CycA/CDK1, so as to coordinatively promote the formation of liver cancer." (PMID 30364632, 2018). "CMC can also down-regulate the expressions of CDK1 and CCNB1, induce G2/M phase cell cycle arrest, and play a role in the treatment of liver cancer through a multi-ingredient, multi-target, and multi-pathway mechanism." (PMID 39806972, 2025). "Overall, our in silico study demonstrates Digoxin’s strong impact on the CDK1/CSK2 complex and offers important insights for the development of more effective and selective therapies against liver cancer." (PMID 41048345, 2025). "We plan to explore how PI3K, AKT, CDK1, CCND1 and RAF1 contribute to arecoline-induced liver cancer using a rat intrahepatic tumor transplantation model and siRNA interference." (PMID 35836300, 2022). "In the TCGA cohort, the GSEA results suggested that high expression of CDK1 and CDK4 was correlated with cell cycle, liver cancer survival, cell cycle checkpoints, DNA replication and cell cycle G2 and M phase transition." (PMID 35193513, 2022).
liver cancer (continued). "The expression of CDK1 was significantly higher in patients than in healthy volunteers, primarily in patients with stage II or III liver cancer." (PMID 35836300, 2022). "The correlation between CDK1, HMMR, PTTG1, and TTK and gene markers for different subsets of immune cells in liver cancer were analyzed through the TIMER-related modules." (PMID 34187556, 2021). "Based on the protein expression data from the HPA, the protein expression levels of CDK1, HMMR, PTTG1, and TTK in liver cancer tissues and normal liver tissues were compared by utilizing the antibodiesCAB003799, CAB002433, HPA008890, and CAB013229." (PMID 34187556, 2021). "Also, CDK1 inhibitor could restrict the growth of liver cancer stem cells." (PMID 33758599, 2021). "The mRNA levels and protein levels of CDK1, HMMR, PTTG1, and TTK were higher in liver cancer tissues compared to normal tissues, which showed excellent diagnostic and prognostic value." (PMID 34187556, 2021). "The immunohistochemistry results confirmed that the protein expression levels of CDK1, HMMR, PTTG1, and TTK were higher in liver cancer tissues than normal liver tissues." (PMID 34187556, 2021). "Our results suggest the potential use of TOP2A, RRM2, NEK2, CDK1, and CCNB1 as prognostic biomarkers in liver cancer." (PMID 34681056, 2021). "The correlation between the mRNA expression of CDK1, HMMR, PTTG1, TTK, and infiltrating immune cells in liver cancer was analyzed by using the TIMER database." (PMID 34187556, 2021). "Subsequent validation suggested TOP2A, RRM2, NEK2, CDK1, and CCNB1 as the prognostic biomarkers of liver cancer." (PMID 34681056, 2021). "Four of these hub genes, including CDK1, HMMR, PTTG1, and TTK, were filtered out as potential biomarkers for diagnosis and prognosis of liver cancer." (PMID 34187556, 2021). "In order to explore the mechanism by which CDKN3 influences the occurrence and development of liver cancer, we used bioinformatics tools to screen genes related to changes in CDKN3, and SPC25, CDK1 and CCNB2 were identified." (PMID 32000807, 2020). "We found that BIRC5, CDK1, NUF2, ZWINT, and SPC24 were highly expressed in liver cancer tissues, whereas expression was weak in normal tissues." (PMID 29190974, 2017). "In addition, the combined effects of CDK1 and other cell cycle-related proteins, such as aurora kinase A (AURKA), are also considered as an important target for the treatment of liver cancer." (PMID 40332418, 2025). "Taken together, these results suggest that galangin may induce apoptosis in liver cancer cells by disrupting the cell cycle through its influence on cell cycle proteins such as CCNB1, CDK4, CDK1, and PLK1." (PMID 38816744, 2024). "Moreover, kaempferol markedly suppresses HepG2 cell proliferation and combats liver cancer by increasing BAX and JUN protein expression and decreasing CDK1 protein levels." (PMID 39221164, 2024). "In human hepatic cancer cells SK-HEP-1, kaempferol increased protein levels of LC3-II, p-AMPK, Atg 5, Atg 7, Atg 12, and Beclin-1 and suppressed protein levels of cyclin-dependent kinase 1 (CDK1), cyclin B, p-Akt, and p-mTOR, altogether resulting in G2/M cell cycle arrest and induction of autophagy." (PMID 36142391, 2022). "Through the construction of a protein interaction network and screening and verification of core targets, it was found that CDK1, SRC, CDK4 and E2F1 mRNA and protein expression levels were overexpressed in liver cancer tissues compared with normal liver tissues." (PMID 36699068, 2022).
liver cancer (continued). "Through the DGIdb, 69 drugs interacted with CDK1, HMMR, and TTK, which might help develop new treatment target for liver cancer therapy." (PMID 34187556, 2021). "In addition to CCNB1, CDK1, CDC45, BUB1B, and CCNA2, we also identified five hub genes in Chinese liver cancer, namely AURKA, KIF11, TOP2A, TPX2, and HMMR, which play a crucial role in regulating the cell cycle." (PMID 34257537, 2021). "The CDK1, HMMR, PTTG1, and TTK were hub genes in liver cancer; hence, they might be potential biomarkers for diagnosis, prognosis, and targeted therapy of liver cancer." (PMID 34187556, 2021). "CDK1 is upregulated in various cancers, including LUSC, LUAD, and liver cancer." (PMID 34307447, 2021). "Furthermore, the relationship between SCNA of the CDK1, HMMR, PTTG1, and TTK and infiltrating immune cells in liver cancer was explored via using TIMER." (PMID 34187556, 2021). "Flavopiridol is an inhibitor of cyclin-dependent kinases (CDKs) (including CDK1, CDK2, CDK4, CDK5, CDK6, CDK7, CDK8, and CDK9) and has been investigated for the treatment of several types of cancers, including leukemia, liver cancer, and renal cancer, in clinical phase 2 trials (24, –, 26)." (PMID 31822599, 2019). "In addition, GEPIA online analysis showed that ESR1, AR, CCNB1, CDK1, AKR1C3 and CCNA2 might become potential target genes for the survival and prognosis of PADP for the treatment of liver cancer." (PMID 35463358, 2022). "Given this substantial number of downregulated tumor suppressors and elevation of cdk1 and cdk4, we conclude that fusion-positive HBLs/HCN-NOSs have more severe liver cancers relative to fusion-negative HBLs." (PMID 39796711, 2024). "The results revealed DNA topoisomerase II alpha (TOP2A), ribonucleotide reductase regulatory subunit M2 (RRM2), never in mitosis-related kinase 2 (NEK2), cyclin-dependent kinase 1 (CDK1), and cyclin B1 (CCNB1) as the hub genes for liver cancer." (PMID 34681056, 2021).
gastric cancer (47 papers, 2012 to 2025). A primary or metastatic malignant neoplasm involving the stomach. "The lymph node metastasis of gastric cancer has been associated with overexpression of Cyclin B1, with one study showcasing the role of CDK1 and Cyclin B1 pathways in the loss of p27 and progression of gastric cancer." (PMID 36769170, 2023). "Pharmacological inhibition of CDK1 effectively disrupts this axis, restoring cisplatin sensitivity and suppressing tumor growth in gastric cancer models." (PMID 41063222, 2025). "Phosphorylation of islet-1 serine 269 by CDK1 can increase its transcriptional activity and promote the proliferation of gastric cancer cells, and inhibition of CDK1 can inhibit the proliferation, migration and invasion of GC cells." (PMID 39371335, 2024). "In gastric cancer, the cell cycle signaling pathway can be activated by overexpressing CDK1, which ultimately affects the development of gastric cancer cells and then affects cancer progression." (PMID 38564630, 2024). "Cell viability was reduced with the knockout of KDF1 and CDK1, supporting their role as oncogenes and potential involvement in promoting gastric cancer progression." (PMID 39171503, 2024). "The same study reported that the inhibitor treatment causes a reduction of COX-2, p-ERK, and p-Akt, implicating the Cyclin B1/CDK1 axis and its involvement in other signaling pathways regulating the growth of gastric cancer cells." (PMID 36769170, 2023). "It has been shown that CAMKK2 works in the MEK/ERK1 signaling cascade alongside CDK1 to achieve the progression of gastric cancer." (PMID 36769170, 2023). "Previous studies have reported the differential expression of the genes we identified in gastric cancer, but few studies have reported the differential expression of AURKB, CCNA2, PLK1, TPX2, and CDK1 in gastric cancer." (PMID 37238607, 2023). "Among natural compounds, flavonoids extracted from Citrus aurantium target Cyclin B1 and CDK1 to induce apoptosis in gastric cancer cells, and have been shown to be potential chemoprevention agents." (PMID 36769170, 2023). "Kaempferol led to a noticeable decrease in the protein levels of cyclin B1, Cdc25C and Cdk1 in a dose-dependent manner in gastric cancer cells." (PMID 37239974, 2023). "Harmaline, an alkaloid, induced G2/M-phase arrest by upregulating cyclin B1 and p-Cdk1 expression in SGC-7901 gastric cancer cells." (PMID 35056723, 2022). "In human gastric cancer cells, suppressing the expression of Cdc25C would promote the cyclin B1/CDK1 complex and result in G2/M arrest." (PMID 35628435, 2022). "CDCA5 was coexpressed with CDK1 in gastric cancer, thereby affecting the normal cell cycle transition and thus leading to the proliferation of gastric cancer cells." (PMID 36004205, 2022). "The overexpression of the CDK1 gene in gastric cancer tissues showed a fold change of 2.544 (P=7.42E − 13) compared to the expression of the gene in normal tissues." (PMID 36090896, 2022). "WFA prevents Cdk1/cyclin B1 complex formation, a critical step of cell cycle progression in gastric cancer, by dephosphorylating Cdk1 at Thr161 and p21 upregulation in glioblastome." (PMID 34485538, 2021). "This is the first time that oxaliplatin has been found to play a role in gastric cancer by inhibiting CDK1 phosphorylation." (PMID 34497808, 2021). "Herein, NDUFC1 knockdown induced gastric cancer cells G2/M phase arrest through regulation of cyclin B1/Cdk1 complex." (PMID 34966665, 2021). "For instance, CASC11 is highly expressed in gastric cancer tissues and is involved in the promotion of the growth, invasion, and metastasis of gastric cancer via the CASC11/miR-340-5p/CDK1 axis." (PMID 33937069, 2021).
gastric cancer (continued). "In gastric carcinoma, high expression of CDK1 had found to lead to poor prognosis and correlated inversely with p27 expression." (PMID 31043166, 2019). "Supporting findings from aggressive gastric cancer clinical samples with elevated SHCBP1, knockdown of SHCBP1 in gastric cancer cells suppresses the expression of CDK1, CDK4, and cyclin D1, consistent with a block at the G1/S phase transition and reduced cell proliferation." (PMID 41009347, 2025). "It has been reported that CDK1 is highly expressed in gastric cancer." (PMID 39371335, 2024). "Additionally, CDCA5 cooperates with cyclin-dependent kinase 1 (CDK1) to promote tumor cell proliferation, migration, and invasion abilities in gastric cancer." (PMID 38658931, 2024). "In gastric cancer tissues, CDK1 and CDCA5 expressions are correlated with each other, and this coexpression has been observed in MGC-803 cells, with the inhibition of one or both of these genes leading to suppression of invasion, migration, colony formation, and proliferation." (PMID 36769170, 2023). "The miR-340-p targets CDK1 directly in gastric cancer cells." (PMID 36769170, 2023). "Moreover, the phosphorylation of ISL-1 via the activity of CDK1 stabilizes ISL-1 in gastric cancer cells." (PMID 36769170, 2023). "This hypothesis is supported by previous data demonstrating that the initial upregulation of cyclin B level, the activator for Cdk1, was followed by a decline upon chelidonine treatment in a gastric cancer cell line." (PMID 34884773, 2021). "The aim of this study was to investigate the expression of cyclin-dependent kinase 1 (CDK1) in gastric cancer (GC), evaluate its relationship with the clinicopathological features and prognosis of GC, and analyze the advantage of CDK1 as a potential independent prognostic factor for GC." (PMID 33365314, 2020). "In this study, we found that in the response of cisplatin to gastric cancer cells, selective inhibition of CDK1 could affect the function of BRCA1, while OXA could play an independent role, indicating that OXA could inhibit CDK1 and thus exert the function of inhibiting BRCA1." (PMID 34497808, 2021). "ESRRA regulates the CD/CDK1/CyclinB1 pathway through DSN1 and promotes the development of gastric cancer." (PMID 38189879, 2024). "Calcium/calmodulin-dependent protein kinase 2 (CAMKK2) works as an upstream factor for CDK1, CDK2, and ERK1 in gastric cancer, as evidenced by bioinformatics analysis." (PMID 36769170, 2023). "Oridonin is a natural compound extracted from Rabdosia rubescens and in gastric cancer cells (SGC-7901); it blocks the cells at the G2/M phase, reducing both Cyclin B1 and CDK1 levels." (PMID 36769170, 2023). "In this study, western blot analysis found that CCNI2 knockdown resulted in reduced AKT phosphorylation level, downregulated CCND1 and CDK1, upregulated MAPK9 expression in gastric cancer cells." (PMID 34895232, 2021). "Flavopiridol, a CDK1 and CDK2 inhibitor, is being clinically tested against gastric cancer, leukemia, and head and neck cancer." (PMID 23320178, 2012). "In this regard, the CDK1 inhibitor p21 was activated, while cyclin D1 inactivated, after overexpression of ZIC1 in gastric cancer cells." (PMID 22799764, 2012). "Strikingly, both CDK1 and SOX9 were upregulated in cisplatin-resistant gastric cancer cell lines." (PMID 41063222, 2025). "In particular, flavonoids isolated from Citrus aurantium were shown to inhibit the growth of human gastric cancer cells, by suppressing the proteins CCNB1 (cyclin B1) and CDK1 which control cell cycle progression; the corresponding genes CCNB1 and CDK1 were found to be upregulated in stomach cancer." (PMID 34422220, 2021).
gastric cancer (continued). "Menadione has been known as an oxidative damage-inducing agent and has been studied in gastric cancer cell lines, where it resulted in proteasome-mediated degradation of Cyclin B1 and CDK1 without reducing the mRNA levels of these genes, with an overall cell cycle arrest in the G2-M phase." (PMID 36769170, 2023). "Everyone is familiar with 11 classic CDKs (CDK1-11), PFTK1 as a new cell cycle dependent kinase is found not along and the connection between PFTK1 and cancers is not much, also in gastric cancer." (PMID 26488471, 2015). "Silbinin extracted from milk thistle is a known flavonolignan compound, and in the gastric cancer cell line (MGC-803), it negatively influenced the STAT3 pathway to activate caspase 3 and caspase 9 activities to induce apoptosis with a negative impact on survival, Cyclin B1, and CDK1." (PMID 36769170, 2023).